TNF (tumor necrosis factor)
Diseases named in the same sentence as TNF in open-access papers (continued):
Sharing a sentence is not in itself a finding about the gene and the disease.
Anxiety (continued). "Their results suggested firstly that high anxiety indexes in EAE mice precede the appearance of motor defects and secondly that TNF-α has a pivotal role in the high anxiety response because of the ability of this cytokine to cause striatum inflammation and microglia activation." (PMID 24312102, 2013). "Experimental studies also show that IL-6, IL-1β, and TNF-α rise in response to acute psychosocial stressors such as the Trier Social Stress Test, and that IL-6 correlates with negative affect and stress-related anger or anxiety." (PMID 41333345, 2025). "Moreover, IL-4Rα inhibition was associated with downregulation of anti-inflammatory cytokines, upregulation of TNF-α and nitric oxide, and altered BDNF expression, collectively contributing to cognitive dysfunction and exacerbated neuroinflammation and anxiety-like behaviours." (PMID 40977748, 2025). "ZSSF treatment dramatically reduced anxiety-like behaviors, exerted sedative–hypnotic effects, increased hippocampal 5-HT and 5-HTP, and enhanced intestinal barrier function through inhibiting colon ZO-1, Claudin-1, and Occludin expression and reducing TNF-α, IL-6, and IL-1β levels." (PMID 40077533, 2025). "Specifically, SARS-CoV-2 infection appears to upregulate multiple pro-inflammatory cytokines and secreted proteins (e.g., CALCA, TNF, PLAT, PPARG), which are known to promote anxiety phenotypes, while anxiety itself may modulate key regulators of viral pathophysiology." (PMID 40766923, 2025). "Bioinformatics analysis shows that these targets are mainly related to the TNF signaling pathway, Estrogen signaling pathway and MAPK signaling pathway, indicating that the active components of Si-ni San are crucial for the pathogenesis of adolescent depression combined with anxiety." (PMID 39247617, 2024). "Compared with those in HHE + S mice, anxiety-like behaviours in L. murinus-treated HHE mice were efficiently alleviated, as indicated by increased time spent in the central area of the open field and in the open arms of the elevated plus maze, and TNF-α expression was decreased in the serum." (PMID 38972900, 2024). "While combined TNF-α and IL-1β administration failed to significantly modulate sickness- and anxiety-like behaviors in the EPM and LDB tests, although there was a trend for less distance travelled by cytokines that was absent in mice pre-treated with the GPR120 agonist." (PMID 38111048, 2023). "TNF-α induced by the hippocampal microglia is significantly elevated in mice exposed to acute stress, and cytokines (IL-1β, TNF-α) released by the microglia can inhibit neurogenesis in the dentate gyrus, thereby promoting neuronal apoptosis and increasing anxiety-related behavior." (PMID 36624089, 2023). "High TNF-α (P=0.002, adjusted P=0.008), but not high IL-1β (P=0.864, adjusted P=1.000), IL-6 (P=0.160, adjusted P=0.640), and IL-17 (P=0.266, adjusted P=1.000), was correlated with anxiety occurrence." (PMID 35239774, 2022). "However, we did observe a baseline shift in anxiety-like behavior in these mice, which was not seen in either the full TNF knockout or the astrocyte-specific knockout." (PMID 36104437, 2022). "Similarly, mice lacking the principal receptor for TNF (TNFR1−/−) also had normal baseline behaviour but no stress-induced elevation in anxiety-like behaviour." (PMID 36104437, 2022). "Our results found that treadmill exercise reduced the level of TNF-α in the striatum, hippocampus and serum of the METH acute withdrawal mice, which may become the main reason for treadmill exercise alleviating anxiety-like symptoms in the METH acute withdrawal period." (PMID 36106141, 2022). "In addition, previous clinical research confirmed that cytokines, namely TNF-α and IL-6, induce depressive mood, anxiety, impaired memory, and lack of concentration." (PMID 31251788, 2019).
Anxiety (continued). "In summary, a possible mechanism for early exercise‐induced neuroprotection against PSA was through regulation of inflammation to promote neurologic recovery and ameliorate anxiety‐like behavior, and proinflammatory cytokines (PAF, IL‐6, and TNF‐α) may play a critical role in the process." (PMID 29201553, 2017). "Additionally, the ameliorations of memory impairment and anxiety by PGRN and thalidomide could be blocked by TNFα ICV injection, thereby indicating the critical role of PGRN/TNFα ratio in the behaviors." (PMID 28300056, 2017). "Interestingly, in SLE patients with depressive symptoms and anxiety symptoms, serum and cerebrospinal fluid (CSF) levels of TNFα were higher than those in patients without depressive symptoms and anxiety symptoms, correlating with poorer health-related quality of life (HRQoL)." (PMID 38164134, 2023). "In our model, even in the absence of direct penetration of PA into the brain, infected mice developed anxiety-like behaviors, which might result from cerebral microvascular dysfunction, BBB leakage, and systemic/local production of cytotoxic cytokines like IL-1β and TNF-α as previously documented." (PMID 37245027, 2023). "Before treatment, significant differences were observed in IL-1, IL-6, TNF-α, LPS, Zonulin, DAO, and I-FABP between patients with FD accompanied by anxiety and those without anxiety (p < 0.05)." (PMID 40606168, 2025). "However, only IL-6 and TNF-α cytokines were identified as relevant pro-inflammatory biomarkers that could differentiate between the groups exhibiting affective symptoms (depressive versus the anxiety/non-depressive group) and the control group." (PMID 30943938, 2019). "Anxiety-like behaviors could not be observed in cKO mice after CFA injection with IL-1β and TNF-α levels not remarkedly increasing." (PMID 39337650, 2024). "Note that the effects of TNF-α on anxiety-like behaviors were not ubiquitous, as Tnfa KO mice exhibited significant anxiety-like behaviors induced by chronic restraint stress (CRS), a well-established stress model of anxiety." (PMID 36917193, 2023).
liver fibrosis (545 papers, 2008 to 2026). "Network pharmacology identified multiple mechanisms underlying Biejiaxiaozheng pills’ anti-liver fibrosis effects, with the TNF signaling pathway as a key contributor." (PMID 40634403, 2025). "The degree of liver inflammation, liver damage, and liver fibrosis in CHB patients is positively linked with higher levels of TNF-α." (PMID 40821631, 2025). "The resolution of liver fibrosis is associated with a decrease in the levels of some cytokines, such as IL-6, IL-1-β, TNF, and TGF-β, in the liver." (PMID 39063116, 2024). "Earlier studies showed a good correlation between cytokine levels and fibrosis stages; higher levels of IL-6 and TNF-α were associated with the presence of advanced liver fibrosis." (PMID 39272729, 2024). "In a hyperglycemic state, the release of inflammatory factors such as IL-6, TNF-α, IL-8, and IL-1β can activate hepatic stellate cells and Kupffer cells, causing liver fibrosis, and can also stimulate cardiac fibroblasts, exacerbating myocardial fibrosis." (PMID 39775020, 2024). "As pro-inflammatory cytokines are directly linked to the development of liver fibrosis 23, the reduction of IL-6, IL-β1 and TNF-α by Tenovin-1 prompted us to test its effects on hepatic fibrosis." (PMID 38993557, 2024). "Accordingly, macrophages and neutrophils constituting the liver fibrosis pathogenic cells are thought to release pro-inflammatory cytokines (IL-1β and TNF-α) upon activation [41." (PMID 36708488, 2023). "Despite these findings, evidence was provided from diet-induced murine NASH models indicating that IFNγ- or Stimulator of interferon genes (STING)-deficiency attenuates steatosis and liver fibrosis, as well as TNFα and IL-6 mRNA liver expression." (PMID 36768637, 2023). "The improvement of liver fibrosis after DAA treatment was associated with higher baseline values of platelet count as well as TNF-α and IL-10 genetic polymorphisms." (PMID 36674897, 2023). "TNF is primarily a group of pro-inflammatory cytokines that are known to be crucial in causing liver fibrosis." (PMID 37111092, 2023). "Another research showed that deltamethrin caused liver fibrosis through inhibition of Nrf2 expression and boost of NF-κB/TNF-α and TGF-β1/Smad3 pathway." (PMID 35126808, 2022). "Gene Set Enrichment Analysis (GSEA) showed an enrichment of pathways associated with inflammation and liver fibrosis in SuHx animals, in particular TNFα signaling, IL6-JAK-STAT3 signaling, Interferon alpha (IFNα) and gamma (IFNγ) response." (PMID 35369312, 2022). "Valproic acid delivery simultaneously caused a significant rise in hydroxyproline, TNF-α production, and NF-kB expression, increasing the risk of liver fibrosis development." (PMID 36435779, 2022). "TNFα has a central role in liver inflammation and metabolic processes, and it constitutes a hallmark in liver fibrosis." (PMID 36423130, 2022). "Advanced hepatic fibrosis is also associated with oxidative stress, which mediates inflammatory cytokines such as tumor necrosis factor-α and interleukin-6." (PMID 34583706, 2021). "Inverse relationship between serum TNFα level and muscle mass further supports the importance of TNFα as a causative factor of liver fibrosis-associated muscle wasting." (PMID 33414474, 2021). "The findings so far have suggested that TNFα present in the bloodstream is the causative factor for skeletal muscle atrophy during liver fibrosis." (PMID 33414474, 2021). "Kupffer cells release proinflammatory cytokines such as TNF-α, IL-6, and IL-1, resulting in the activation of hepatic satellite cells, a hallmark event in liver fibrosis." (PMID 34707781, 2021). "As one of the important pathways associated with inflammatory response and hepatic fibrosis, its activation can lead to the release of downstream inflammatory factors and induce the production of TNF-α, IL-1β, and IL-6." (PMID 34803712, 2021).
liver fibrosis (continued). "In the liver fibrosis caused by CCl4, the levels of mRNA encoding inflammatory factors F4/80, IL-6, IL-1β, and TNF-α reached a high value at 12 weeks." (PMID 33117360, 2020). "In adult populations, TNFα has been linked to parameters of metabolic deterioration, steatohepatitis and liver fibrosis." (PMID 28859076, 2017). "Inflammatory cytokines such as TNF-α, IL-6, and IL-1β are the main factors controlling the inflammatory response that causes liver damage and liver fibrosis." (PMID 28594374, 2017). "It was also demonstrated that irradiation increased the susceptibility of hepatocytes to TNF-α-mediated apoptosis through cell–cell interaction, leading to liver fibrosis." (PMID 24914105, 2014). "TNF-α, IL-6, and interleukin-1 beta (IL-1β) are proinflammatory cytokines that work in a vicious cycle with NF-κB signaling pathways to promote one another and intensify the inflammatory response, causing liver fibrosis." (PMID 40552161, 2025). "TNFα has been associated with the pathogenesis of chronic liver inflammation with the activation of local hepatic stellate cells into fibrogenic myofibroblasts, leading to liver fibrosis." (PMID 38540717, 2024). "The present data indicated that BECs TLR3 deficiency resulted in significantly increased IL-6 and TNF secretion induced by CsEVs, which may be an important reason for more severe liver damage and liver fibrosis in TLR3-/- mice infected with C. sinensis." (PMID 37167198, 2023). "These authors concluded that these results may have been influenced by ethnic variations and that the TNF-α (-G308A) polymorphism can be associated with hepatic fibrosis." (PMID 36820674, 2023). "In addition, other liver flukes infection, such as Opisthorchis viverrini, also result in high expression of IL-6 and TNF-α, and is closely associated with the development of liver fibrosis." (PMID 36693049, 2023). "TNFR1 is the major membrane receptor of TNF-α, and its activation further promotes the activation of downstream NF-κB and inflammasome and increases inflammatory factor expression, while the TNF-α-mediated inflammatory response is also one of the important causes of liver fibrosis progression." (PMID 35371052, 2022). "Thus, it is widely accepted that TNF-α is implicated in chronic liver inflammation that leads to liver fibrosis." (PMID 35329997, 2022). "Tumor necrosis factor (TNF) is a proinflammatory cytokine secreted from activated macrophages and involved in many aspects of the regulation of the immune response, including the survival of HSCs, which are associated with enhanced liver fibrosis." (PMID 34298967, 2021). "In line with this hypothesis, subjects falling into the high-risk group for liver fibrosis had higher circulating levels of inflammatory biomarkers such as TNF-α." (PMID 34829846, 2021). "In this study, we investigated the effect of ER stress-induced TNF-α production by KCs on the apoptosis of active HSCs, as well as the possible underlying mechanism, and aimed to identify new treatments to reverse the progression of hepatic fibrosis." (PMID 32802876, 2020). "Previous studies have shown that the antifibrosis effect of a type of ginsenoside AD-2 extracted from ginseng on thioacetamide-induced liver injury in mice is related to the inflammatory factors (including TNF-α, IL-1β, caspase-1, and IL-6) associated with hepatic fibrosis." (PMID 32724321, 2020). "There is also evidence that ACEs could alleviate TGF-β-induced early liver fibrosis caused by alcohol treatment and protect liver from injury caused by TNF-α activation-mediated acetaminophen toxicity." (PMID 30781399, 2019). "Preoperative serum inflammatory mediators (such as IL6, IL8, and TNF-α) may be associated with liver fibrosis and cirrhosis." (PMID 31781194, 2019). "TNF-α can prompt the activation of HSCs in rats, causing liver fibrosis." (PMID 28594374, 2017). "Indeed, circulating levels of TNF-α are elevated in patients with liver fibrosis and are associated with a poor prognosis." (PMID 27046197, 2016).
liver fibrosis (continued). "This TNF-α-dependent mechanism could lead to faster progression of liver fibrosis and cirrhosis, which are the main causes of morbidity and mortality in patients with HCV infection." (PMID 27175704, 2016). "After menopause women change from an estrogen protective milieu, where HCV-mediated inflammation is controlled, to a hepatic proinflammatory state where estrogen levels drop and IL-6 and TNF-α cytokines levels greatly increase possibly increasing the risk of hepatic fibrosis progression." (PMID 26090666, 2015). "The release of TNF-α causes inflammation, which leads to liver fibrosis." (PMID 24400890, 2014). "Given that elevated inflammation due to TNF-α, IL-6 and IL-1β are amongst the causative factors of liver fibrosis and liver steatosis, and high levels of TNF-α, IL-6 and IL-1β are known to deregulate glucose metabolism, we measured the levels of these cytokines in the liver." (PMID 24260182, 2013). "TNF-alpha is thought to aggravate hepatic fibrosis caused by Schistosoma mansoni." (PMID 18001742, 2008). "Intra-hepatic TNF-α has been previously associated with liver fibrosis, and the accumulation of cells expressing this marker may explain in part the faster rate of liver disease progression found in HCV/HIV co-infection." (PMID 18941622, 2008). "However, more studies are needed to confirm that TRAF2 may accelerate the progression of HBV-associated liver fibrosis by encouraging the release of the inflammatory factors TNFα and IL8 through the TAK1/P38 or TAK1/NF-kB signaling pathways." (PMID 37091870, 2023). "TNFα-induced mouse lung fibrosis resolution is associated with reduced numbers of alternatively activated macrophages as well as reprogramming of alternatively activated macrophages into “restorative” macrophages, similar to what has been observed in spontaneous resolution of hepatic fibrosis." (PMID 33688918, 2021). "The antifibrotic effect of daclatasvir and sofosbuvir by downregulation of the tumor necrosis factor alpha (TNF‐α)/nuclear factor kappa B (NF‐κB) pathway might have caused regression of liver fibrosis and contributed to the observed decrease in liver stiffness." (PMID 33535495, 2021). "Thus, TNFα signalling inhibition may alleviate liver fibrosis and the associated complications by exerting an anti-fibrotic effect on the liver and an anti-atrophic effect on the skeletal muscle." (PMID 33414474, 2021). "Mouse models of liver fibrosis induced by BDL or toxic injury show that depletion of Tregs leads to enhanced inflammatory cytokine production (TNF‐α and IL‐17) and increased recruitment of fibrogenic macrophages and effector T cells, worsening fibrosis." (PMID 41487942, 2026). "Network pharmacology identified IL-1β, IL-6, and TNF-α as potential targets for YQHX in treating liver fibrosis.The UPLC detected multiple potential active components." (PMID 41296792, 2025). "Activated inflammatory cells in the liver, such as Kupffer cells and macrophages, release various pro-inflammatory cytokines, including tumor necrosis factor-alpha (TNF-α) and interleukin-6 (IL-6), which exacerbate hepatocyte damage and promote liver fibrosis." (PMID 40538532, 2025). "Currently, extensive research is investigating strategies to mitigate the progression of liver fibrosis, including the use of receptor antagonists or the reduction of IL-1β and TNF-α levels in vivo." (PMID 41296792, 2025). "TNF-α is an inflammatory mediator produced by immune cells and, when abnormally expressed, promotes the development of hepatitis and liver fibrosis." (PMID 41281287, 2025). "Actually, reactive oxygen species (ROS) stimulate the production of TNF-α, which in turn impairs cell function, resulting in liver fibrosis and necrosis." (PMID 39758360, 2025). "Adipokines such as TNF-α, leptin, and resistin can be disrupted by lower levels of thyroid hormone in circulation, exacerbating liver fibrosis." (PMID 40006040, 2025).